ZFAS1 (ZNFX1 antisense RNA 1)
Diseases named in the same sentence as ZFAS1 in open-access papers (continued):
Sharing a sentence is not in itself a finding about the gene and the disease.
lymph node metastasis (17 papers, 2016 to 2023). "Exosomal HOTTIP was reported to be associated with poor overall survival, while exosomal ZFAS1 was associated with lymph node metastasis and poorer clinical stage." (PMID 35465325, 2022). "In the case of skin melanoma, higher ZFAS1 expression was associated with higher clinical stage, primary tumor thickness, and with the presence of lymph node metastases." (PMID 31010087, 2019). "Then, they found higher ZFAS1 expression were significantly associated with advanced tumor differentiation grade, lymph node metastasis, advanced TMN stage and a poorer prognosis." (PMID 30186041, 2018). "From the pooled results, we found that overexpression of ZFAS1 was significantly associated with positive lymph node metastasis (OR = 4.18, 95% CI: 2.70-6.48, p<0.001) and advanced clinical stage (OR = 3.36, 95%CI: 1.69-6.65, p<0.001)." (PMID 28977885, 2017). "Increased ZFAS1 expression was significantly associated with vascular invasion (OR = 2.26, 95% CI = 1.36–3.78, P = 0.002), lymph node metastasis (OR = 2.98, 95% CI = 2.12–4.19, P < 0.001) and advanced TNM stage (OR = 3.00, 95% CI = 2.18–4.12, P < 0.001)." (PMID 29245995, 2017). "A number of studies have revealed that zinc finger antisense 1 (ZFAS1), a long noncoding RNA (lncRNA), is aberrantly regulated in various cancers, and high ZFAS1 expression is associated with poor prognosis and increased risk of lymph node metastasis (LNM)." (PMID 29137442, 2017). "In 6 studies, the association of ZFAS1 with lymph node metastasis was also investigated." (PMID 30544408, 2018). "Further analysis revealed that the expression level of ZFAS1 gradually increased with late stage and lymph node metastasis (p < 0.05)." (PMID 34980191, 2022). "It was found that the elevated expression of ZFAS1 was correlated to lymph node metastasis (pooled OR = 2.84, 95% CI = 1.53–5.27, P = .001)." (PMID 30544408, 2018). "They found the higher ZFAS1 expression were correlated with tumor thickness, lymph node metastasis, tumor stages in poor disease-free survival time (DFS) or over survival (OS) of melanoma patients." (PMID 30186041, 2018). "Furthermore, the elevated ZFAS1 expression was significantly related to positive lymph node metastasis (OR = 4.18, 95% CI: 2.70-6.48, p< 0.001)." (PMID 28977885, 2017). "Also plasma ZFAS1 level was associated with TNM stage, cancer invasion, lymph node metastasis and distant metastasis." (PMID 27654478, 2016). "Moreover, it analyzed the relationship between ZFAS1 and pathological features, including lymph node metastasis, gender, histological grade, and TNM stage.However, through careful analysis, we found that there were still some shortcomings in these system reviews." (PMID 30544408, 2018). "In addition, abnormal expression of lncRNA ZFAS1 was related to TNM stage and lymph node metastasis in LAD patients." (PMID 32515146, 2020). "However, there was heterogeneity between the expression of ZFAS1 and TNM stage and lymph node metastasis." (PMID 30544408, 2018).
esophageal squamous cell carcinoma (15 papers, 2017 to 2025). Esophageal squamous cell carcinoma (ESCC) is a type of esophageal carcinoma (EC) that can affect any part of the esophagus, but is usually located in the upper or middle third. "Exosomal ZFAS1 has also been declared to regulate the proliferation, invasion, migration, and apoptosis of esophageal squamous cell carcinoma by regulating the miRNA-124/STAT3 axis." (PMID 35090549, 2022). "A previous study demonstrated that lncRNA ZFAS1 was highly expressed in the tissues of esophageal squamous cell carcinoma, and exosomes with ZFAS1 overexpression significantly promoted cell-based xenograft tumor growth." (PMID 35168607, 2022). "This study aimed to examine the prognostic value of the lncRNA ZFAS1 in esophageal squamous cell carcinoma (ESCC)." (PMID 28938617, 2017). "Since ZFAS1 has already been studied in esophageal cancer, such as exosomal ZFAS1 promoting proliferation, migration, and invasion of esophageal squamous cell carcinoma by upregulating STAT3 and downregulating miR-124 while inhibiting apoptosis, we chose ZC3H18 for further investigation." (PMID 40070828, 2025). "ZFAS1 has been shown to promote the proliferation, migration, and invasion of esophageal squamous cell carcinoma (ESCC) cells, and to inhibit their apoptosis by upregulating STAT3 and downregulating miR-124." (PMID 36545127, 2022). "For example, in esophageal squamous cell carcinoma (ESCC), lncRNA ZFAS1 is elevated in cancer tissues and can be transmitted among cancer cells via exosomes." (PMID 34819615, 2021). "Functionally, lncRNA ZFAS1 promotes esophageal squamous cell carcinoma (ESCC) cell proliferation, invasion, migration and induced apoptosis." (PMID 32515146, 2020). "In recent years, long non-coding RNAs (lncRNAs) are of great importance in development of different types of tumors, while the function of lncRNA ZFAS1 is rarely discussed in esophageal squamous cell carcinoma (ESCC)." (PMID 31775815, 2019). "In esophageal squamous cell carcinoma (ESCC), ZFAS1 can shuttle between tumor cells in the form of exosomes and act as ceRNA to downregulate miR-124, thereby upregulating STAT3 and ultimately inhibiting cellular apoptosis and promoting proliferation, migration, and invasion." (PMID 37178254, 2023). "In recent days, some studies also reported that ZFAS1 plays a vital role in other cancers such as melanoma, non-small cell lung cancer (NSCLC), osteosarcoma (OS), esophageal squamous cell carcinoma (ESCC), acute myeloid leukemia (AML) and natural killer/T cell lymphoma (NKTCL)." (PMID 30186041, 2018).
osteosarcoma (15 papers, 2017 to 2025). A usually aggressive malignant bone-forming mesenchymal neoplasm, predominantly affecting adolescents and young adults. "Although previous study had revealed that ZFAS1 acted as a risk factor in osteosarcoma tumorigenesis, the downstream regulatory pathway of ZFAS1 is still unclear." (PMID 29262629, 2017). "Taken together, ZFAS1 expression was significantly up-regulated in osteosarcoma patients and predicted the poor prognosis, indicating the risk factor of ZFAS1 in osteosarcoma genesis." (PMID 29262629, 2017). "Furthermore, we observed that both miR-520b and miR-520e were lowly expressed in osteosarcoma tissues compared with that in normal tissues (n = 8), and their expression levels were negatively associated with Lnc-ZFAS1 expression." (PMID 36473367, 2023). "Higher levels of ZFAS1 or SRSF3 were linked to a poor prognosis of osteosarcoma." (PMID 35184675, 2022). "Taken together, loss-of-functional experiments revealed that ZFAS1 knockdown could inhibit the proliferation of osteosarcoma cells." (PMID 29262629, 2017). "Thus, we performed loss-of-functional experiments to test the function of ZFAS1 on proliferation of osteosarcoma cells in vitro." (PMID 29262629, 2017). "We found that LncRNA ZFAS1 was upregulated in osteosarcoma, and Lnc-ZFAS1 overexpression facilitated osteosarcoma cells proliferation, migration, invasion and EMT, while Lnc-ZFAS1 silence exerted reverse influence." (PMID 36473367, 2023). "To expose the fundamental mechanism through which Lnc-ZFAS1 affects osteosarcoma progression, we first examined the subcellular location of Lnc-ZFAS1 in KHOS cells and found Lnc-ZFAS1 was evenly enriched in the and nucleus." (PMID 36473367, 2023). "Our findings indicate that Lnc-ZFAS1 acted a functional role in osteosarcoma progression through targeting RHOC." (PMID 36473367, 2023). "Taken together, our findings further confirmed the accelerated role of Lnc-ZFAS1 in osteosarcoma cells migration, invasion, and EMT." (PMID 36473367, 2023). "To explore the role of Lnc-ZFAS1 in osteosarcoma, we first analyzed the expression level of Lnc-ZFAS1 in osteosarcoma tissues and normal tissues in TCGA database." (PMID 36473367, 2023). "Lnc-ZFAS1 was upregulated in osteosarcoma tissues, which was further confirmed in clinic samples by q-PCR analysis (n = 8)." (PMID 36473367, 2023). "Overall, these findings suggested that Lnc-ZFAS1 facilitates osteosarcoma cell proliferation and restrains its apoptosis." (PMID 36473367, 2023). "We demonstrated the Lnc-ZFAS1/miR-520b/miR-520e/RHOC axis involved in the development of osteosarcoma." (PMID 36473367, 2023). "Our findings provided Lnc-ZFAS1/miR-520b/RHOC and Lnc-ZFAS1/miR-520e/RHOC axes as potential therapeutic strategies against osteosarcoma." (PMID 36473367, 2023). "In this work, we identified miR-520b and miR-520e as the target miRNAs of Lnc-ZFAS1 and found these two miRNAs were downregulated in osteosarcoma." (PMID 36473367, 2023). "Among miRNAs downregulated in osteosarcoma, hsa-miR-520b, hsa-miR-520e and hsa-miR-934 was identified as the potential target of Lnc-ZFAS1." (PMID 36473367, 2023). "Following that, we discovered that ZFAS1 levels were substantially higher in 10 of our collected osteosarcoma tissues when compared to matched adjacent normal tissues." (PMID 35184675, 2022). "In our present study, we investigated the biological function of ZFAS1 in osteosarcoma cells proliferation and metastasis and its related molecular mechanism." (PMID 35184675, 2022). "Silencing of ZFAS1 represses osteosarcoma cells proliferation and metastasis, and induces cell apoptosis." (PMID 35184675, 2022). "ZFAS1 was found to be significantly overexpressed in osteosarcoma patient samples, according to data from the TCGA database." (PMID 35184675, 2022). "The role of ZFAS1 regulated osteosarcoma cells proliferation and metastasis through SRSF3 was subsequently explored." (PMID 35184675, 2022).
osteosarcoma (continued). "This study discovered that ZFAS1 was upregulated in osteosarcoma patient tissues, which correlates with elevated SRSF3 protein levels." (PMID 35184675, 2022). "This correlation was consistent with previous research, indicating that ZFAS1 plays an essential role in osteosarcoma." (PMID 35184675, 2022). "Our findings suggest that ZFAS1 plays a pro-oncogenic role in osteosarcoma and can be employed as a biomarker and therapeutic target in the disease treatment." (PMID 35184675, 2022). "Functional studies revealed that ZFAS1 knockdown inhibited osteosarcoma cell proliferation as measured by the CCK-8 assay, colony formation assay, and Ki-67 immunofluorescence staining." (PMID 35184675, 2022). "Based on the findings of this study, the role of ZFAS1 in osteosarcoma cells proliferation and metastasis was established through the stabilization of alternative splicing factor SRSF6." (PMID 35184675, 2022). "IT has also been observed that ZFAS1 knockdown inhibited osteosarcoma cell migration and invasion as measured by the wound healing assay and the trans-well assay with or without Matrigel." (PMID 35184675, 2022). "ZFAS1 was found to be upregulated in osteosarcoma and be positively correlated with SRSF3 protein levels." (PMID 35184675, 2022). "U2OS cells were transfected with ZFAS1 siRNA or control siRNA to establish the impact of ZFAS1 on osteosarcoma cells’ metastasis." (PMID 35184675, 2022). "We also found that ZFAS1 levels were considerably higher in 10 of our collected osteosarcoma tissues when compared to matched adjacent normal tissues." (PMID 35184675, 2022). "ZFAS1 has the potential to be used as a prognostic biomarker as well as a therapeutic target in the treatment of osteosarcoma." (PMID 35184675, 2022). "Our findings show that ZFAS1 plays an essential role in osteosarcoma progression by stabilizing the SRSF3 protein." (PMID 35184675, 2022). "In osteosarcoma, ZFAS1 was observed directly interacting with ZEB2 protein and then regulated the stability of ZEB2, thereby leading to increased cell growth and metastasis." (PMID 33202381, 2020). "Functional experiments revealed that upregulated ZFAS1 promoted osteosarcoma cell proliferation, migration, and invasion in vitro and in vivo." (PMID 30288832, 2019). "Kaplan‐Meier analysis suggested that osteosarcoma patients with high ZFAS1 levels had shorter overall survival (OS) than those with low ZFAS1." (PMID 30288832, 2019). "In osteosarcoma cell, ZFAS1 suppression markedly inhibited cell proliferation, led cycle arrest at G0/G1 phase, and promoted apoptosis in vitro, and inhibited the tumor growth in vivo." (PMID 29678899, 2018). "For osteosarcoma, we aimed to investigate the expression levels of ZFAS1 in osteosarcoma tissue from clinical samples." (PMID 29262629, 2017). "Our present studies discover a novel regulatory pathway of ZFAS1 targeting miR-486 for diagnosis, prognosis, and therapy of osteosarcoma." (PMID 29262629, 2017). "Our study revealed the over-expression of ZFAS1 in osteosarcoma tissue and found the correlation of ZFAS1 up-regulation with poor prognosis, providing an effective diagnostic approach." (PMID 29262629, 2017). "It had been testified that ZFAS1 was up-regulated in osteosarcoma tissue, and the high expression level of ZFAS1 was closely correlated with poor prognosis." (PMID 29262629, 2017). "In conclusion, our results demonstrate that ZFAS1 act as competing endogenous RNA (ceRNA) for miR-486, and act as oncogene in osteosarcoma tumorigenesis, and discover the functional regulatory pathway of ZFAS1 sponging miR-486." (PMID 29262629, 2017). "Firstly, RT-PCR showed that ZFAS1 expression in osteosarcoma cell lines (U2OS, Saos-2, HOS and MG63) were significantly up-regulated compared to normal human osteoplastic cell line (NHOst)." (PMID 29262629, 2017).
osteosarcoma (continued). "In present study, we utilize lncRNA microarray assay to screen the lncRNA expression profile in osteosarcoma tissue, and investigate the regulatory function of ZFAS1 in osteosarcoma." (PMID 29262629, 2017). "In summary, our study revealed the up-regulated expression of ZFAS1 in osteosarcoma tissue and cells, suggesting the tumor promoting factor of ZFAS1 in osteosarcoma genesis." (PMID 29262629, 2017). "Because the role of ZFAS1in osteosarcoma tumorigenesis was still unclear, thus, we chose ZFAS1 as the research target." (PMID 29262629, 2017). "To verify the interaction of ZFAS1 on osteosarcoma patient survival rate, we calculated the overall survival (OS) rate and recurrence-free survival (RFS) rate with post-surgical follow-up." (PMID 29262629, 2017). "In present study, we have uncovered the oncogenic role of ZFAS1 on osteosarcoma progression in vitro." (PMID 29262629, 2017). "For further investigation, we sequentially verified the role of ZFAS1 knockdown on apoptosis and cell cycle of osteosarcoma cells using flow cytometry." (PMID 29262629, 2017). "In present study, we detected the ZFAS1 expression in 53 cases of osteosarcoma patients and found the up-regulated expression of ZFAS1." (PMID 29262629, 2017). "Collectively, our data demonstrated that Lnc-ZFAS1 might function as a ceRNA to sponge miR-520b and miR-520e in osteosarcoma." (PMID 36473367, 2023). "To verify whether Lnc-ZFAS1 acts oncogenic driver in osteosarcoma progression in an RHOC-dependent manner, we co-transfected Lnc-ZFAS1 siRNA and RHOC overexpression plasmids into KHOS cells." (PMID 36473367, 2023). "We further investigated the effects of Lnc-ZFAS1 on osteosarcoma cell migration and invasion." (PMID 36473367, 2023). "Thus, in this work, we examined the expression of Lnc-ZFAS1 in osteosarcoma and comprehensively evaluated its effects on osteosarcoma in vitro." (PMID 36473367, 2023). "As a member of the RHO family, Ras Homologue C (RHOC) has been proven to participate in the occurrence and progression of osteosarcoma, whereas whether Lnc-ZFAS1 mediates RHOC in osteosarcoma remains unclear." (PMID 36473367, 2023). "Collectively, these results suggest that Lnc-ZFAS1 is highly expressed in osteosarcoma." (PMID 36473367, 2023). "In addition, we detected the expression level of Lnc-ZFAS1 in osteosarcoma cell lines U2OS and KHOS, as well as the human osteoblast cell line hFOB1.19 and found the expression of Lnc-ZFAS1 was significantly higher in U2OS and KHOS cells than in hFOB1.19 cell." (PMID 36473367, 2023). "Lnc-ZFAS1 was upregulated in osteosarcoma and Lnc-ZFAS1 could exert promoted impact upon osteosarcoma cells proliferation, migration, invasion, and EMT in vitro." (PMID 36473367, 2023). "To summarize, our paper concluded that Lnc-ZFAS1 was upregulated in osteosarcoma and Lnc-ZFAS1 could exert promoted impact upon osteosarcoma cells proliferation, migration, invasion and EMT in vitro." (PMID 36473367, 2023). "In this study, our findings suggested Lnc-ZFAS1 as an oncogenic driver in osteosarcoma progression." (PMID 36473367, 2023). "Consistently, our results demonstrated that Lnc-ZFAS1 was upregulated in osteosarcoma, and Lnc-ZFAS1 could significantly facilitate the osteosarcoma cells' proliferation, migration and invasion in vitro." (PMID 36473367, 2023). "Compilation of these findings suggests that ZFAS1 promotes osteosarcoma progression through SRSF3." (PMID 35184675, 2022). "We hypothesized in our study that the lncRNA ZFAS1 promotes osteosarcoma by directly binding to and stabilizing SRSF3." (PMID 35184675, 2022). "Functional studies demonstrated that ZFAS1 depletion could inhibit osteosarcoma cells proliferation and metastasis through SRSF3." (PMID 35184675, 2022). "ZFAS1 promotes tumorigenesis in osteosarcoma through miR-646/NOB1." (PMID 35184675, 2022). "Recent studies have demonstrated an elevated expression of ZFAS1 in osteosarcoma." (PMID 35184675, 2022).